HMGB1 (high mobility group box 1)
Diseases named in the same sentence as HMGB1 in open-access papers (continued):
Sharing a sentence is not in itself a finding about the gene and the disease.
colorectal cancer (continued). "Our primary objective in this study was to design an oncolytic HSV expressing HMGB1 to kill colorectal cancer cell lines, in particular during hypoxia; however, HSV-HMGB1 failed to destroy HT29 cells at MOI 0.1 under hypoxic conditions." (PMID 35477503, 2022). "In the log rank test, the serum HMGB1 level did not correlate with prognosis (P = 0.336), but the serum CEA level was correlated with the survival rate of colorectal cancer patients (P<0.0001)." (PMID 22496788, 2012).
melanoma (141 papers, 2012 to 2026). A malignant, usually aggressive tumor composed of atypical, neoplastic melanocytes. "GSDME expressed by the pyroptostic cell the combined treatment of BRAF and MEK inhibitors in melanoma can elevate the amount of T cells and DCs, while GSDME-deficient melanoma exhibited less HMGB1 release and BRAFi and MEKi resistance." (PMID 40064873, 2025). "It has been shown that oHSV-induced ICD of both melanoma and squamous cell carcinoma cells resulted in the release of damage-associated molecular patterns (DAMPs) such as ATP and high mobility group protein B1 (HMGB1) in vitro." (PMID 38921005, 2024). "MIA is a secretory protein, inextricably linked with invasion and metastasis in melanoma cells and its expression is enhanced by HMGB1 through interaction with NF-κB p65." (PMID 37511951, 2023). "Hypoxia-induced macrophage polarization is HMGB1-dependent, significantly increasing the number of tumor-associated macrophages with an M2-like phenotype in HMGB1-positive murine and human melanomas." (PMID 37465676, 2023). "Higher HMGB1 levels showed a positive correlation with mitotic index, which in turn is linked to advanced stages of melanoma." (PMID 36012593, 2022). "UV exposure significantly reduced the susceptibility of melanoma cells to CD8+ T cell-dependent cytotoxicity through activation of the HMGB1/TBK1/IRF3/NF-κB cascade which in turn triggers the PD-1/PD-L1 checkpoint." (PMID 36012593, 2022). "GSDME-deficient melanoma showed defective HMGB1 release, decreased tumor-associated T cells, and activated DC infiltrates in response to BRAFi + MEKi, and more frequent tumor regrowth was observed after drug removal." (PMID 35739593, 2022). "GSEME-deficient melanoma exhibited defective HMGB1 release, decreased T cells and elevated dendritic cell infiltration." (PMID 36032140, 2022). "Nevertheless, our data suggest that polarization toward the M1-like phenotype is caused, in part, by extracellular HMGB1 from Salmonella-treated melanoma cells." (PMID 34207850, 2021). "Previous studies have reported that HMGB1 is associated with melanoma initiation and progression, further suggested HMGB1 as a potential therapeutic target for melanoma therapy." (PMID 32536835, 2020). "Collectively, these results indicate that HMGB1-dependent production of IL-10 by tumour-associated M2-like macrophages contributes to tumour progression in our mouse melanoma model." (PMID 27426915, 2016). "By inhibiting oxygen-sensitive prolyl hydroxylases (PHDs) with DMOG, we observed that the resulting increased stabilization of HIF1α was associated with a higher HMGB1 release in melanoma cell lines." (PMID 27426915, 2016). "To gain a better understanding of this association, we examined the correlation of the HMGB1 level and the melanoma stage." (PMID 25051367, 2014). "There were significantly higher staining of proliferation markers Ki-67 and PCNA in HMGB1-proficient melanoma tumors than HMGB1-deficient tumors." (PMID 25051367, 2014). "This close association of a high level of HMGB1 with the late disease stage prompted us to examine its relationship with the melanoma patient prognosis." (PMID 25051367, 2014). "In agreement with the oncogenic role of HMGB1, we found a close association of HMGB1 with human melanoma in that the expression of HMGB1 increased progressively during the development of human melanoma." (PMID 25051367, 2014). "Taken together, our data implicate an oncogenic function of the intracellular HMGB1, which is associated with an increased cell proliferation in human melanoma tissues." (PMID 25051367, 2014). "Although HMGB1 enhances promoter activity in melanoma cells, the functional role of HMGB1 in tumor progression and its association with clinical outcome of cancer patients is still not fully understood." (PMID 25051367, 2014). "Higher HMGB1 levels are associated with significantly poorer overall and melanoma-specific 5-year survival (p<0.001)." (PMID 25051367, 2014).
melanoma (continued). "We show that HMGB1 appeared to be required in support of melanoma cell proliferation because reduced HMGB1 expression caused marked cell cycle arrest and senescence." (PMID 25051367, 2014). "Taken together, these data suggest a tight association between melanoma with an elevated rate of cell proliferation with increased HMGB1 expression." (PMID 25051367, 2014). "HMGB1 upregulated was known to be negatively associated with melanoma survival." (PMID 35896522, 2022). "Interestingly, GSDME‐deficient melanoma represents defective HMGB1 release, the reduced infiltration of tumor‐associated T cells and activated DCs in response to BRAFi + MEKi treatment, and the more frequent tumor regrowth after drug removal." (PMID 34459122, 2021). "Moreover, HMGB1 is both secreted by tumor cells and found within many tumors including prostate cancer, melanoma, lung and colon cancer, and is associated with poor prognosis." (PMID 30123419, 2018). "Although laboratory studies have implicated the high mobility group box 1 (HMGB1) in melanoma, its clinical relevance remains unclear." (PMID 25051367, 2014). "To test the data derived from in vitro studies for the clinical relevance, we examined whether there was any association between HMGB1 and p21 expression in human melanomas." (PMID 25051367, 2014). "The association of HMGB1 protein abundance with highly elevated mitotic index from melanoma patient samples led us to ask whether this high mobility protein might contribute to melanoma cell proliferation." (PMID 25051367, 2014). "In addition, it has been shown that T-VEC induces immunogenic cell death in melanoma cell lines with the associated release of damage-associated molecular patterns (DAMPs), as measured by release of high mobility group box-1 (HMGB-1), adenosine triphosphate (ATP) and ecto-calreticulin (CRT)." (PMID 34777344, 2021). "The expression of HMGB1 in melanoma tissues was measured by immunohistochemistry, and the results indicated that HMGB1 was transferred from the nucleus to the cytoplasm and extracellular matrix." (PMID 41114460, 2026). "In vitro studies found that R.E treatmentnotonly induces dose-dependent cytotoxicity in B16F10 melanoma cellsbut also stimulates the release of DAMPs, ATP and HMGB1." (PMID 41341044, 2025). "In melanoma, hypoxia leads to cell necrosis and release of HMGB1, which interacts with RAGE to activate M2-type macrophages to secrete interleukin-10 (IL - 10), thereby promoting melanoma growth and metastasis." (PMID 40969278, 2025). "It underscores the central role of the HMGB1/RAGE-IL-23-IL-17-IL-6-Stat3 in the progression of melanoma." (PMID 38529373, 2024). "Shikonin promotes the release of HSP70, HSP90, and HMGB1 in melanoma cells by enhancing immunogenic apoptosis." (PMID 39759512, 2024). "Studies have shown that IRE treatment of pancreatic cancer and melanoma cells resulted in the release of the DAMP molecules HMGB1 and ATP in the culture media, resulting in immunologic cell death." (PMID 39766257, 2024). "In glioblastoma, clear cell renal cell carcinoma, gastric cancer, nasopharyngeal carcinoma, melanoma, and non-small cell lung cancer, the HMGB1/RAGE axis plays a role in tumor metastasis through the MAPK signaling pathway." (PMID 38529373, 2024). "The results in H1975 resemble the previous report of necroptosis and HMGB1 release after caspase inhibition and irradiation in mouse melanoma cells." (PMID 37346039, 2023). "MiR-548b and its targeted HMGB1 gene suppressed melanoma growth, migration and invasion in melanoma tissues." (PMID 36982460, 2023).
melanoma (continued). "MiR-548b, by targeting the HMGB1 gene, suppressed melanoma cell migration and invasiveness in vitro." (PMID 36982460, 2023). "In conclusion, miR-548b, through inhibiting the expression of HMGB1, significantly contributes to melanoma suppression." (PMID 36982460, 2023). "HMGB1 released from pyroptotic melanoma cells induced the activation of dendritic cells (DCs) and antitumor T cells, which in turn prevented melanoma growth." (PMID 36387211, 2022). "HMGB1 was released passively in the extracellular space by dying cells both in wild-type and BRAF mutated melanoma cells." (PMID 36012593, 2022). "HMGB1 is a direct target of miR-548b, and the expression level of this miRNA can suppress melanoma cells’ growth by targeting the HMGB1 pathway." (PMID 36012593, 2022). "HMGB1, released by melanoma cells, promotes the accumulation of M2-macrophages, which enrich the tumoral microenvironment with IL-10, turning down the tumoral killing." (PMID 36012593, 2022). "It was also noted that higher levels of HMGB1 correlate with more severe disease stages and with worse survival rates in melanoma patients." (PMID 36012593, 2022). "Recent data have demonstrated that keratinocytes secrete a high mobility group box 1 (HMGB1) protein, which promotes neutrophils infiltration into the melanoma microenvironment, being responsible for melanoma plasticity." (PMID 35334544, 2022). "Since HMGB1 directly induces IL-10 production in TAMs, blocking IL-10 with a neutralizing antibody led to delayed tumor growth in a B16 mouse melanoma model." (PMID 36012593, 2022). "We also examined the cellular response to BNCT in human melanoma A375 cells and analyzed HMGB1 levels in the culture supernatant at 6 and 24 h post-neutron irradiation in BPA-pretreated cells." (PMID 35336794, 2022). "ALO was demonstrated to exert protective effects in melanoma-promoting cell apoptosis via the inhibition of HMGB1 release in melanoma cells." (PMID 36012593, 2022). "Peptide Rb4, derived from protein proteolipid protein 2 (PLP2), acts directly on tumor cell multiplication inducing the expression of two DAMPs molecules, HMGB1 and calreticulin, which trigger immunoprotective effects in vivo against melanoma cells." (PMID 36012593, 2022). "The combinations of BRAF inhibitors and MEK inhibitors (BRAFi + MEKi) caused durable regression of melanoma by promoting cleavage of GSDME and the release of HMGB1." (PMID 35739593, 2022). "A study conducted to evaluate the differences in the sera between responder and non-responder patients demonstrated an early increase in eosinophil counts as well as a decrease in S100A8/A9 and HMGB1 in responding melanoma patients." (PMID 36012593, 2022). "Namely, miR-26a is involved in the upregulation of dabrafenib efficacy via an HMGB1-dependent autophagy pathway in melanoma." (PMID 36012593, 2022). "The treatment with a miR-26a mimic and HMGB1 shRNA increased the efficacy of dabrafenib in melanoma cells, according to one study." (PMID 36012593, 2022). "RAGE/HMGB1 axis also activates T lymphocytes, as demonstrated by a study with animal specimens: the study showed that the HMGB1/RAGE axis influences melanoma growth via the expression of IL-23 and IL-17 from a subpopulation of T cells, (γδ-T cells)." (PMID 36012593, 2022). "Taking the wild type mouse melanoma cell line (B16) and HMGB1 knockout type B16HMGB1− as the detection matrix, the serum of the SS patients with ANA-IF presented nuclear fine speckled (AC-4) pattern reran the IIFT." (PMID 35411013, 2022). "We have previously identified constitutive DAMPs (HMGB1 and Calreticulin) as well as new putative inducible DAMPs such as Haptoglobin (HP), from a therapeutically used heat shock-conditioned melanoma cell lysate (called TRIMEL)." (PMID 35805888, 2022). "Once secreted by melanoma cells, HMGB1 binds to RAGE, activating the endothelial cells with consequent increased expression of the adhesion molecules VCAM-1, ICAM-1, and E-selectin." (PMID 36012593, 2022).
melanoma (continued). "In order to further confirm that the anti-HMGB1 antibody is one of the characteristic autoantibodies of SS, we used the Cas9 technique to construct an HMGB1 knockout mouse melanoma cell line B16HMGB1− to repeat the ANA-IF experiment." (PMID 35411013, 2022). "Recently, melanoma cells subjected to ultraviolet radiation (UVR) were shown to release HMGB1 which subsequently activated RAGE to promote nuclear factor-κB (NF-κB)-dependent transcription of PD-L1 in melanoma cells." (PMID 34488792, 2021). "This time, we neutralized LPS in Salmonella-treated melanoma cells using Polymyxin B and then measured HMGB1 in the culture supernatant." (PMID 34207850, 2021). "In mouse melanoma cells and several other cell lines, doxorubicin treatment induced senescence in an HMGB1-dependent manner." (PMID 33558529, 2021). "Markedly, GSDME pores mediated the leakage of DAMPs including high mobility group protein B1 (HMGB1) from the melanoma cells." (PMID 33634141, 2021). "The recruitment of M2 macrophages in a hypoxia-dependent manner was observed in VEGF- and HMGB1 (high mobility group box 1)-secreting melanoma cells." (PMID 33918883, 2021). "We suggested that ALO induced melanoma cell apoptosis by inhibiting release of HMGB1 release and activation of ERK signal pathway." (PMID 32536835, 2020). "Researchers corroborated this data with results obtained from the patients who showed a higher risk of melanoma metastasis that positively correlated with an elevated level of neutrophil infiltration found in the primary tumor, which could be a result of increased HMGB1 secretion." (PMID 33171792, 2020). "HMGB1 is notably increased in the serum of patients with metastatic melanoma and is released by melanoma cells under hypoxic conditions, promoting melanoma growth and metastasis." (PMID 32436353, 2020). "Altogether, our study demonstrated that ALO plays an important role in promoting apoptosis of melanoma cells by inhibiting HMGB1 release and activation of downstream ERK signal pathway." (PMID 32536835, 2020). "Previous studies have demonstrated that HMGB1 promotes melanoma cell survival through activating the downstream ERK signal pathway, in this study, we further tested the effect of ALO on this signal pathway." (PMID 32536835, 2020). "The expression of PD-L1 allowed melanoma cells to evade CD8+ T cell-mediated cytotoxicity that was preventable by blockade of HMGB1/RAGE activation or by programmed death (PD)-1/PD-L1 blockade." (PMID 32664328, 2020). "Meanwhile, pyroptosis can also release inflammatory factors such as HMGB1 that are highly expressed in human melanoma, and promote the progress of melanoma." (PMID 33133646, 2020). "Previous studies found that HMGB1 is highly expressed in human melanoma tissue and suggested it as a potential therapeutic target for melanoma treatment." (PMID 32536835, 2020). "UV irradiation also induced ICD of B16/F10 melanoma cells, as indicated by HMGB1 release and upregulation of MHC-II and CD86, which remained higher even upon poly I:C addition, on cDC1s exposed to B16/F10 TCL." (PMID 30961656, 2019). "Third, it is interesting to further examine the role of other RAGE ligands, such as high mobility group box-1 and S100 proteins in melanoma growth in nude mice." (PMID 31565056, 2019). "In the current investigation, we found that oncolytic NDV/FMW elicits the induction of several known ICD markers, such as CRT exposure, ATP secretion, and HMGB1 as well as HSP70/90 release in melanoma cells." (PMID 31192135, 2019). "It is widely accepted that HMGB1 promotes proliferation and migration (metastasis) of several tumor types, including breast, colon and skin (melanoma)." (PMID 31247032, 2019). "Though mEHT promoted the release of damage-associated molecular pattern (DAMP) damage signaling molecules hsp70, HMGB1 and ATP to potentiate the tumor immunogenicity of melanoma allografts, it reduced MHC-I and melan-A levels in tumor cells." (PMID 31426515, 2019).